IL33 (interleukin 33)
Diseases named in the same sentence as IL33 in open-access papers (continued):
Sharing a sentence is not in itself a finding about the gene and the disease.
tumor (continued). "Local production of IL-33 induced intratumoral accumulation of ILC2s in mice and stimulated ILC2s to secrete CXCR2 ligands that further caused tumor cell-specific apoptosis." (PMID 34209038, 2021). "IL-33-dependent tumor-infiltrating ILC2s have been demonstrated to mediate tumor immune surveillance in cooperation with DCs in promoting adaptive cytolytic T cell responses and controlling tumor metastasis in mice." (PMID 34884995, 2021). "Considering the dual function of IL-33, optimal targeting strategies should be developed to suppress the pro-tumorigenic effects while driving anti-tumor activities of IL-33 preferentially, depending on the specific environmental context." (PMID 34209038, 2021). "Our current data suggest that Eomes inhibits T cell-mediated immune responses in the TME in the setting of IL33-based tumor immunotherapy." (PMID 33553191, 2021). "Ablation of Il33 gene expression in Cxcl13-Cre-positive FSCs reduces the functionality of intratumoral T cells and unleashes tumor growth." (PMID 34354077, 2021). "Overexpression of active IL33 in tumor cells, administration of IL33 protein, as well as checkpoint inhibitor-induced tumor cell-derived IL33 inhibited tumor growth in multiple tumor models." (PMID 33553191, 2021). "In the report, interleukin-33 (IL-33) was further identified as the effector that dominates environmental damage-induced early neoplasia and neoplastic transformation in the presence of KRAS mutation." (PMID 34023857, 2021). "A review of the literature showed a paucity of reports involving IL-33/ST2 or SDF1/CXCR4 signaling to target TME for tumor progression." (PMID 34298657, 2021). "Our study further demonstrated that Eomes inhibited tissue residency molecules in the setting of IL33 tumor therapy." (PMID 33553191, 2021). "Another study by Wagner and colleagues demonstrated, through in vivo experiments, that the balance between IL-33/ILC2s/eosinophils and tumor lactate (LA) production is fundamental in regulating tumor growth." (PMID 34680190, 2021). "In their in vivo study, suppressive properties of Treg cells were attenuated in IL33−/− Treg cells, facilitating tumor regression in a ST2-independent manner." (PMID 34209038, 2021). "We used CRC as a model to address a putative role of tumor-derived IL-33 on ILC2 functions in the context of tumor immunity." (PMID 33953160, 2021). "IL-33 has been characterized as a functionally ambivalent cytokine that influences the differentiation of immune cells within the tumor microenvironment." (PMID 34504486, 2021). "Lung recruitment of eosinophils was observed post administration of IL-33 in mice, which prevented the onset of pulmonary metastasis and suppressed primary melanoma tumor growth." (PMID 34884995, 2021). "We demonstrate that IL-33 catered by Cxcl13-Cre+ FSCs to tumor-infiltrating CD8+ T cells reduces local T cell exhaustion and thereby sustains control of tumor growth." (PMID 34354077, 2021). "To study the role of Eomes in IL33-driven antitumor immunity, we implanted B16 and B16-IL33 tumor cells into control and CD4cre Eomesflox/flox mice (EKO)." (PMID 33553191, 2021). "The role of IL-33 in neoplasia has been poorly investigated; however, different studies have reported both pro- and antitumorigenic functions." (PMID 34071419, 2021). "The accumulation of OPN can promote the proliferation of tumor cells, which counteracts the antitumor effect of IL‐33 in the tumor microenvironment." (PMID 34664425, 2021). "Here, we showed that efficacy of the IL33-based tumor immunotherapy was greatly enhanced in mice with T cell-specific Eomes deficiency." (PMID 33553191, 2021). "Although ILC2s accumulate around tumors and IL-33 administration activates ILC2s to reduce tumor size, tumors prevent ILC2 functions by several mechanisms." (PMID 33403383, 2021).
tumor (continued). "MCs activated by tumor-derived IL-33 have been reported to promote gastric cancer progression through macrophage mobilization and MC-derived chymase has been shown to promote lung tumor cell EMT phenotype in vitro." (PMID 34884995, 2021). "IL-33/ST2 signaling exerts its effect by potently remodeling the tumor micro-environment (TME) by recruiting immune cells that secrete a diverse collection of molecules." (PMID 33946554, 2021). "Mechanistic studies reveal that IL-33 stimulates contact-dependent degranulation of eosinophils and resultant killing of tumor cells." (PMID 34359674, 2021). "It has been shown that Il33 plays a role in tumor growth, metastasis, neo-angiogenesis, and evading programmed cell death." (PMID 32455670, 2020). "Conversely, IL-33 suppresses tumor growth and metastasis in mouse melanoma, lung carcinoma and mammary carcinoma." (PMID 32340025, 2020). "To confirm that eosinophils are indispensable for the IL-33-induced reduction in tumor growth we argued that repopulation of ∆dblGATA-1 mice with eosinophils would restore the tumor growth-reducing effect." (PMID 32923137, 2020). "The repopulation of tumor-bearing ∆dblGATA-1 mice with eosinophils revealed that significantly smaller tumors developed only in mice that were injected with IL-33-activated eosinophils." (PMID 32923137, 2020). "Our data show that the presence of eosinophils is mandatory for IL-33-induced tumor reduction in models of CRC and that the mechanisms include eosinophil recruitment, activation and degranulation." (PMID 32923137, 2020). "Evidence linking IL‐33 to tumor promotion includes preclinical models and human prognostic associations." (PMID 32566227, 2020). "The earlier the pathologic T stage (American Joint Committee on Cancer [AJCC] staging system) of the tumor was, the higher the expression level of IL-33 was." (PMID 33634017, 2020). "They reported that IL-33/ST2 axis in tumor microenvironment contributes to invasion and metastasis in left-sided CRC, most likely by the interaction between can associated fibroblasts and epithelial tumor cells and activating desmoplasia." (PMID 32246094, 2020). "The net effect of IL-33 on cancer and its progression depends on the type of tumor and its microenvironment." (PMID 32363166, 2020). "Mechanistically, the ability of IL-33 to induce tumor-reactive IFN-γ+ CD107+ CD8+ T and NK cells was recently shown to be dependent on MyD88 signaling in a mouse model of Lewis lung carcinoma." (PMID 33329534, 2020). "In this review, we summarize the most recent advances on anti-tumor immune mechanisms operated by IL-33, including the modulation of immune checkpoint molecules, with the aim to understand its potential as a therapeutic target in cancer." (PMID 33329534, 2020). "In the TME, the potential sources of IL-33 were epithelial cells (including normal epithelial cells and tumor cells), endothelial cells, pericytes, fibroblasts, and smooth muscle cells." (PMID 33634017, 2020). "Specifically, stroma-derived IL-33 acts as a pro-tumor factor, while epithelium-derived IL-33 acts as an antitumor factor." (PMID 33634017, 2020). "Interleukin (IL)-33 has recently emerged as a cytokine that is able to inhibit the development of tumors through eosinophils and other cells of the tumor microenvironment thereby positively influencing disease progress." (PMID 32923137, 2020). "Invalidating ST2 in mice or IL-33 in MC-38 colon cancer cells impedes anti-tumor effects of anti-PD-1 mAb." (PMID 33261061, 2020). "Combination of IL-33 and anti-PD-1 reduced tumor growth and improved the survival of PDAC mice in an ILC2-dependent fashion." (PMID 33329534, 2020). "In conclusion, our study suggests that eosinophils play an indispensable role in the tumor growth-reducing effect of IL-33 in models of CRC." (PMID 32923137, 2020). "Another study showed that IL-33 serves a pivotal role in the functional stability of suppressive Tregs in the tumor microenvironment." (PMID 32363166, 2020).
tumor (continued). "The expression level of IL-33 in tumor samples from female patients was higher than that in tumor samples from male patients (p = 0.002)." (PMID 33634017, 2020). "Tumour-derived IL-33 activates mast cells and macrophages, promoting the development of gastric cancer." (PMID 33308251, 2020). "Induction of IL-33 production by stromal cells following LCMV-based vector immunotherapy elicited protective anti-tumor CD8+ T cell effector responses." (PMID 33329534, 2020). "Monocytic MDSCs increased and granulocytic MDSCs decreased after IL-33 treatment in tumour-bearing mice compared with that in the control group, albeit not significantly." (PMID 33308251, 2020). "The increase in tumor-infiltrating eosinophils in mice exposed to CTX/anti-PDL1/2 correlates with intratumoral expression of IL-33 which can both recruit and activate these cells." (PMID 32290265, 2020). "In this mini review, we will focus on the anti-tumor effects of IL-33/ST2, with emphasis on the most recent advances on immune mechanisms and their potential exploitation for future therapeutic options." (PMID 33329534, 2020). "IL-33 promotes colorectal cancer cell growth and liver metastasis by regulating the tumor microenvironment." (PMID 32993787, 2020). "Migration to the TME can be mediated by eotaxins (eotaxin-1/CCL11, eotaxin-2/CCL24, eotaxin-3/CCL26) that bind the CCR3 receptor highly expressed on eosinophils and by alarmins (i.e., HMGB1 and IL-33) released from dying tumor cells." (PMID 33329534, 2020). "As indicated in the study, animals bearing tumors expressing the IL-33 crippled for nuclear localization showed significantly longer overall survival consistent with very low tumor burden." (PMID 33447733, 2020). "IL-33 can significantly enhance the recruitment of immunosuppressive immune cells into the tumor site, where these cells have a strong impact on immune microenvironment remodeling." (PMID 32246094, 2020). "HCC developed aggressively in the IL-33-treated experimental group, as reflected by the gross view of the mice and tumour." (PMID 33308251, 2020). "Flow cytometry confirmed a significant increase in CD11b+/Gr1− macrophage in IL-33+ tumors as compared to sham-injected controls or vector control tumor-bearing mice." (PMID 33020472, 2020). "M2 cell recruitment and macrophage polarization are promoted by the tumor microenvironment, for example, through the release of IL-33." (PMID 33371444, 2020). "A more recent investigation has showed that the IL-33/Treg axis significantly contribute to the creating of tumor-promoting immune environment as seen in chronic inflammation condition." (PMID 32246094, 2020). "It is possible that a decrease in sST2 in the orthotopic tumor microenvironment activates IL-33/ST2L signaling in stellate cell-TAM or CAF-TAM interactions, which results in the suppression of Cxcl3 expression." (PMID 32340025, 2020). "Here, we examined if the enrichment of chemokines and the increase in Iba1+ cells, observed in IL-33+ syngeneic and xenograft mouse brains were associated with recruitment of circulating immune cells into the IL-33+ tumor environment." (PMID 33020472, 2020). "Strikingly, all these studies demonstrated anti-tumor effects of anti-IL33 and anti-ST2 antibody treatments." (PMID 32719677, 2020). "This idea was strengthened by showing that using a similar PDAC model, the cytokine required, i.e., IL-18 or IL-33, depends on the site of injection, that is to say the tumor microenvironment." (PMID 33261061, 2020). "Exogenously administered recombinant mouse IL-33 significantly induces ST2-positive Tregs accumulated in tumor masses." (PMID 32246094, 2020). "In the present study, the effect of extracellular IL-33 at a high concentration (20 ng/ml) from either cancer cells or CAFs released into the tumor microenvironment of CCA inhibited cancer cell migration." (PMID 33046978, 2020).
tumor (continued). "Significant increases in the percentage of CD11c+ and CD11c+CD11B+ DCs were found in tumour-bearing mice treated with IL-33." (PMID 33308251, 2020). "Using differential levels of CD45 to distinguish between resident and infiltrating immune cells, we found a striking increase in the presence of CD45high cells within the tumor-bearing hemisphere of IL-33+ vs. IL-33− syngeneic mice." (PMID 33020472, 2020). "The current literature suggests that the anti-tumor properties of IL-33 are attributable to its capacity to stimulate CD8+ T cells, NK, DC, eosinophils and ILC2." (PMID 33329534, 2020). "The total number of isolated CD45+ leukocytes was two-fold higher in IL-33+ vs. IL-33− 1492 tumor-bearing mice." (PMID 33020472, 2020). "IL-33, a cytokine involved in the regulation of anti-tumor immunity and tumor growth, its levels are significantly higher in EC patients than that of healthy volunteers." (PMID 33014844, 2020). "In bone marrow-derived DC cell transfer or Tc9 cell transfer therapeutic models, IL-33 injection delays tumor growth." (PMID 33261061, 2020). "We recently explored the anti-tumor activity of IL-33, a cytokine known to induce tumoricidal functions in eosinophils on bone marrow-derived murine basophils." (PMID 33013885, 2020). "IL-33 preferentially promotes Th2 response, which is classically believed to contrast tumor immunity, although its role appears ambivalent." (PMID 33329534, 2020). "Further research is required to uncover other MC-activating factors present in the tumor microenvironment and how they impact IL33 signaling and MC activation." (PMID 32719677, 2020). "We propose a working model where the most abundant IL33 responsive immune cell type is likely to dictate an overall tumor-supporting or tumor suppressing outcome in vivo." (PMID 32719677, 2020). "Transgenic expression of IL-33 in B16 or 4T1 tumor cells or in the host, as well as exogenous administration of the recombinant protein induce the recruitment of activated (IFN-γ+ CD107+) CD8+ T and NK cells in the TME, which inhibited tumor growth in mice." (PMID 33329534, 2020). "The mechanism of IL-33 was explained in terms of tumour microenvironment remodelling, secretion of factors promoting tumour proliferation, and microvascular density." (PMID 33308251, 2020). "To further elucidate the potential mechanism by which tumor cell-derived TNF-α promotes IL-33 expression in CAFs, we examined the expression of TNF-α receptors (TNFR1 and TNFR2) in both GC cells and CAFs." (PMID 31659258, 2020). "IL‐33 levels were found to be increased and correlated with tumor development, suggesting that IL‐33 is a potential marker for a poor prognosis." (PMID 32566227, 2020). "The immunoregulatory molecules cytotoxic T-lymphocyte antigen 4 (CTLA-4), programmed death receptor 1 (PD-1), and programmed death ligand 1 (PD-L1) were also higher in high IL-33 tumor samples than in low IL-33 tumor samples." (PMID 33634017, 2020). "Taken together, these results suggested that tumor cell-derived TNF-α promotes the expression of IL-33 in CAFs via the TNFR2/NF-κB/IRF-1 pathway." (PMID 31659258, 2020). "Intratumor IL-33 can directly act on cancer cells or indirectly act on the tumor microenvironment (TME)." (PMID 33634017, 2020). "In further agreement with the tumor-promoting effect of type 2 immunity in the gut, IL-33 transgenic mice inoculated with MC38 cells exhibited an increased cell proliferation, an effect driven via cyclooxygenase (COX)/PGE2." (PMID 33371444, 2020). "IL-33 administration markedly increased CD45+ leukocyte immune cell infiltration on day 11 after the tumour challenge." (PMID 33308251, 2020). "In this case, the anti-apoptotic activity of IL-33 in gastric tissue exposed to carcinogenic H. pylori infection can be deleterious to the host due to promotion of neoplasia." (PMID 32151084, 2020). "IL-33 favoured lymphocyte invasion of the tumour microenvironment, thus, promoting tumour growth and angiogenesis." (PMID 33308251, 2020).
tumor (continued). "The protumor activity of ILC2s is mainly attributed to IL-33-driven IL-4 and IL-13 production from these cells which have been reported to support tumor development and progression." (PMID 33233582, 2020). "IL-33-dependent ILC2 tumor infiltration drove intra-tumoral dendritic cell accumulation, collectively improving anti-tumor immunity." (PMID 32695313, 2020). "Last, stromal IL‐33 facilitates tumor metastases and invasion by suppressing local antitumor immunity, which is mediated by intratumor accumulation of Tregs and ILC2s." (PMID 32566227, 2020). "In fact, the present study demonstrated that activation of the IL-33/ST2L axis by suppressing sST2 in the tumor microenvironment inhibited orthotopic tumor growth of Panc02 cells." (PMID 32340025, 2020). "Tumor cell-derived IL-33 stimulated IL-13 secretion by ILC2s that enhanced DC antigen presentation and generation of anti-tumor CTL." (PMID 32903717, 2020). "Using ΔdblGATA-1 mice, we further show that the effects of IL-33-induced tumor reduction are dependent on the presence of eosinophils." (PMID 32923137, 2020). "We found that interferon-γ (IFN-γ) and CYT, which reflect the activity of the antitumor immune response, were higher in high IL-33 tumor samples." (PMID 33634017, 2020). "In the presence of immunosuppressive factors (e.g. tumour growth factor-β), tumour stromal IL-33 plays an immunosuppressive role through Tregs and MDSCs." (PMID 33308251, 2020). "IL-33-activated ILC2s sustain CXCR2 expression on tumor cells by producing high amounts of CXCR2 ligands, which, in turn, induce apoptosis in malignant cells." (PMID 33138017, 2020). "Cerebral leukocytes were isolated from IL-33+ and IL-33− tumor-bearing hemispheres, sorted for CD45, and RNA sequenced using the 10× Chromium platform." (PMID 33020472, 2020). "In contrast, by using models of lung metastasis, IL-33-dependent ILC2s promote tumor burden and metastasis, mainly regulating type 1 activity of lung NK cells." (PMID 33233582, 2020). "While it is possible that IL-33 is released from dying cancer cells in the necrotic regions of tumors, we do not see major signs of necrosis in our models especially when tumor burden is very small." (PMID 33447733, 2020). "IL-33, as an effective vaccine adjuvant combined with human papilloma virus vaccine enhances anti-tumour immunity of CD8+ T cells in vivo." (PMID 33308251, 2020). "Our findings showed that IL-33 enhances the extended survival of eosinophils in the CRC tumor microenvironment both in vitro and in vivo." (PMID 32923137, 2020). "Although there was a slight difference in the IL-6 and TNF-α mRNA levels, the IL-1β cytokine levels were elevated in tumours injected with IL-33." (PMID 33308251, 2020). "Tissue resident ST2-expressing cells, like MCs and ILC2s are the dominant IL33 responders during the early stages of tumor development." (PMID 32719677, 2020). "Meanwhile, IL-33 increased the splenic infiltration of immunosuppressive cells in tumour-bearing mice." (PMID 33308251, 2020). "IL-33 is elevated in CRC, both in tissue and serum samples, and the IL-33/ST2L axis shapes immune cell populations in the tumor, promoting the accumulation or depletion of immunosuppressive and anti-tumorigenic cells, respectively." (PMID 33371444, 2020). "In another study, inoculation of IL-33-expressing EL4, CT26 or B16.F10 tumor cells induced MyD88-dependent intratumoral expansion of ILC2 in mice that were indispensable for IL-33-mediated antitumor activity independently of eosinophils." (PMID 33329534, 2020). "Knock-out of IL-33 in Panc02-injected mice reduced the proportion of mice with visible metastatic nodules to the lungs by approximately 50%, highlighting the importance of IL-33/NF-κB/MMP9 axis in tumor metastasis." (PMID 32752017, 2020). "First, leukocytes were isolated from the tumor-bearing hemisphere of IL-33+ and IL-33− 1492 syngeneic mice, and characterized using flow cytometry." (PMID 33020472, 2020).